HMGB3 (high mobility group box 3)
Diseases named in the same sentence as HMGB3 in open-access papers (continued):
Sharing a sentence is not in itself a finding about the gene and the disease.
colorectal cancer (13 papers, 2017 to 2025). A primary or metastatic malignant neoplasm that affects the colon or rectum. "HMGB3 is also known to be associated with the Wnt/β-catenin signaling pathway in both hematopoietic stem cells and in cancer cells, including in epithelial ovarian cancer, cervical cancer, and colorectal cancer." (PMID 41009989, 2025). "To investigate the mechanism of HMGB3 knockdown-mediated colorectal cancer inhibition, we detected that knockdown of HMGB3 decrease mesenchymal markers (N-cadherin, Vimentin) as well as the key factors of WNT/β-catenin signaling pathway (β-catenin)." (PMID 35712661, 2022). "To investigate the mechanism of HMGB3 knockdown-mediated colorectal cancer inhibition, we detected a downregulation of N-cadherin, Vimentin and β-catenin proteins after knockdown of HMGB3." (PMID 35712661, 2022). "Previous studies have pointed out the important role of HMGB3 in tumors, and how it works in colorectal cancer needs to be studied in depth." (PMID 35712661, 2022). "We found that HMGB3 can play important roles in colorectal cancer such as proliferation and migration, and can play corresponding roles through the WNT/β-catenin signaling pathway." (PMID 35712661, 2022). "By mediating high mobility group box 3 (HMGB3) miR-429 promotes apoptosis in colorectal cancer cells." (PMID 36158660, 2022). "In this study, we investigated the expression and prognosis of HMGB3 in colorectal cancer patients in the cBioPortal and GEPIA2 databases." (PMID 35712661, 2022). "HMGB3 was found to be aberrantly expressed in most cancers and highly expressed in most tumors, including colorectal cancer." (PMID 35712661, 2022). "Our results suggest that HMGB3 is correlated with the proliferation and migration of colorectal cancer cells and can be a possible new prognostic indicator and therapeutic target for CRC patients." (PMID 35712661, 2022). "We also constructed an siRNA plasmid as well as an overexpression plasmid of HMGB3 to verify the mechanism of HMGB3 in colorectal cancer by in vitro cytological assays." (PMID 35712661, 2022). "The same study has showed the involvement of HMGB3 in carcinogenesis and development of colorectal cancer mediated via WNT/β-catenin pathway and suggests HMGB3 to be a promising therapeutic target of colorectal cancer." (PMID 31581454, 2019). "HMGB3 may promote the progression of colorectal cancer (CRC) through the activation of WNT/β-catenin/c-Myc signaling." (PMID 39062899, 2024). "Moreover, HMGB3 promotes tumor development by regulating Wnt/β-catenin signaling in cervical cancer, non-small cell lung cancer, and colorectal cancer." (PMID 37328851, 2023). "We found that HMGB3 is highly expressed in colorectal cancer in both a state." (PMID 35712661, 2022). "In addition, we analyzed the methylation of HMGB3 and other profiles to explore the potential mechanisms of HMGB3 in colorectal cancer." (PMID 35712661, 2022). "We explored the expression abundance of HMGB3 in colorectal cancer cell lines." (PMID 35712661, 2022). "HMGB3 has also been reported as a potential prognostic marker in colorectal cancer." (PMID 33960364, 2021). "To explore the relationship of specific clinical index information, we performed a correlation analysis using the survival prognosis of 140 colorectal cancer patients with TMA and found that high expression of HMGB3 had a poor prognosis." (PMID 35712661, 2022).
nasopharyngeal carcinoma (13 papers, 2016 to 2025). A carcinoma arising from the nasopharyngeal epithelium. "Knockdown of HMGB3 has been shown to inhibit proliferation, angiogenesis, and metastasis of nasopharyngeal carcinoma." (PMID 39390359, 2024). "Our research aims to investigate how ELAVL1 controls the glycolytic process in nasopharyngeal carcinoma cells through the HMGB3/β-catenin pathway." (PMID 39390359, 2024). "ELAVL1 promotes glycolysis in nasopharyngeal carcinoma cells by interacting with HMGB3 to stabilize HMGB3 mRNA, thereby activating β-catenin pathway." (PMID 39390359, 2024). "In this study, we determined the regulatory role of ELAVL1 in the glycolytic process of nasopharyngeal carcinoma cells via the HMGB3/β-catenin axis." (PMID 39390359, 2024). "For instance, SNHG5 has been found to promote nasopharyngeal carcinoma development via regulating miR-1179/HMGB3 axis." (PMID 34863279, 2021). "HMGB3 promotes glycolysis by activating β-catenin pathway in nasopharyngeal carcinoma cells." (PMID 39390359, 2024). "Furthermore, our findings revealed that HMGB3 has the capacity to stimulate glycolysis in nasopharyngeal carcinoma cells by activating the β-catenin pathway." (PMID 39390359, 2024). "However, there is limited research investigating the regulation of glycolysis by HMGB3 in cells of nasopharyngeal carcinoma." (PMID 39390359, 2024). "HMGB3 is involved in ELAVL1-mediated glycolysis in nasopharyngeal carcinoma cells." (PMID 39390359, 2024). "In addition, our experiments revealed that the suppressive impact of sh-ELAVL1 on the glycolytic ability of nasopharyngeal carcinoma cells was reversed upon subsequent overexpression of HMGB3." (PMID 39390359, 2024). "These discoveries lead us to propose a hypothesis that ELAVL1 interacts with HMGB3 to enhance its stability, thereby promoting aerobic glycolysis in nasopharyngeal carcinoma cells by further activating the β-catenin pathway." (PMID 39390359, 2024). "In nasopharyngeal carcinoma, HMGB3 may regulate tumor development through the LncRNA-SNHG5/miR-1179 signaling axis." (PMID 39062899, 2024). "Moreover, the transfer of high mobility group box 3 (HMGB3) from nasopharyngeal carcinoma cells to endothelial cells via EVs induces angiogenesis." (PMID 35059436, 2021). "Similarly, SNHG5 in nasopharyngeal carcinoma regulates the expression of both the miR-1179/HMGB3 axis and cancer progression." (PMID 32947877, 2020). "Notably, in nasopharyngeal carcinoma cells, HMGB3 expression is significantly upregulated." (PMID 39390359, 2024). "nEXOs overexpress high mobility group box 3 (HMGB3), which promotes nasopharyngeal carcinoma metastasis by accelerating angiogenesis, and HMGB3 provides inspiration for finding markers of nasopharyngeal carcinoma metastasis." (PMID 36275738, 2022). "By conducting qRT-PCR analysis of 30 pairs of clinical specimens from nasopharyngeal carcinoma and non-tumor patients, the elevated expression of HMGB3 in nasopharyngeal carcinoma was confirmed." (PMID 39390359, 2024).
cervical cancer (10 papers, 2016 to 2025). A primary or metastatic malignant neoplasm involving the cervix. "HMGB3 knockdown markedly increased the susceptibility of the cervical cancer cells to cisplatin (DDP), paclitaxel (TAX) and vincristine (VIN) treatment, resulting in a significant reduction in IC50 value and a reduced colony formation." (PMID 33187536, 2020). "Multivariate Cox proportional hazards model analysis indicated that HMGB3 expression was an independent prognostic risk factor in cervical cancer patients (HR = 23.48, 95% CI: 3.21–171.94, P = 0.0019)." (PMID 33187536, 2020). "miR-758 triggers tumor growth and metastasis in cervical carcinoma through interaction with HMGB3 and the Wnt/β-catenin signaling pathway." (PMID 39062899, 2024). "A positive correlation (R = 0.385, P = 1.5 × 10− 5) between HMGB3 and hTERT was observed in 119 cervical cancer patients from tissue microarray." (PMID 33187536, 2020). "In this study, we examined the regulation of HMGB3 on cervical cancer cell proliferation and apoptosisafter exposing to radiation, and also explored its underlying mechanism including of DNA damage pathways." (PMID 33187536, 2020). "In this study, we have identified HMGB3/hTERT signaling axis as a new target for cervical cancer radioresistance." (PMID 33187536, 2020). "The results from xenograft mouse model further supported that the HMGB3-mediated radioresistance depended on its transcriptional regulation of hTERT in cervical cancer." (PMID 33187536, 2020). "In our study, we showed that HMGB3 was highly expressed in cervical cancer radioresistant cells and HMGB3 knockdown significantly enhanced the susceptibility of cervical cancer cells to radiation in vivo and in vitro." (PMID 33187536, 2020). "We also showed that hTERT and HMGB3 possessed the same subcellular colocalization, and were highly expressed in the cervical cancer radioresistant cells." (PMID 33187536, 2020). "Here, we have identified HMGB3/hTERT signaling axis as a new target for cervical cancer radioresistance." (PMID 33187536, 2020). "Firstly, the published gene expression profile of cervical cancer (GSE56363) indicated a positive correlation between hTERT and HMGB3 in the cervical cancer patients undergoing radiotherapy (R = 0.44, P = 0.047)." (PMID 33187536, 2020). "We then recruited 53 cervical cancer patients undergoing radiotherapy to evaluate the correlation between therapeutic responses and HMGB3/hTERT expression." (PMID 33187536, 2020). "The patients who had a high HMGB3 expression similarly displayed a higher percentage of high hTERT expression, hinting the potential regulation of hTERT by HMGB3 in cervical cancer." (PMID 33187536, 2020). "Firstly, HMGB3 knockdown suppressed hTERT expression, while its overexpression upregulated hTERT expression in cervical cancer cells." (PMID 33187536, 2020). "In summary, our study has revealed the crucial role of HMGB3 in radioresistance and prognosis in cervical cancer." (PMID 33187536, 2020). "HMGB3 knockdown also inhibited the binding of H3K4me3, a chromatin activation marker, at the hTERT promoter in cervical cancer cells." (PMID 33187536, 2020). "We next determined the effect of HMGB3 on sensitivity of cervical cancer cells to three common chemotherapeutic drugs." (PMID 33187536, 2020). "To validate that the HMGB3-mediated cervical cancer radioresistance depends on its regulation on hTERT, we next performed the rescue experiments in cervical cancer cells and mouse model." (PMID 33187536, 2020). "A protein band (~ 25 kDa) with high binding activity at the hTERT promoter was identified as HMGB3 in RR cervical cancer cell lines." (PMID 33187536, 2020). "The HMGB3/hTERT axis is important for resistance to radiation therapy in cervical cancer." (PMID 39062899, 2024). "Finally, we also analyzed the relationship between HMGB3/hTERT signalling axis and clinical outcome in the cervical cancer patients." (PMID 33187536, 2020).
cervical cancer (continued). "HMGB3 knockdown-mediated radiosensitization could be reversed by the overexpressed hTERT in both cervical cancer cell lines and xenograft tumor mouse model." (PMID 33187536, 2020). "Taken together, these data indicated that HMGB3 transcriptionally upregulated hTERT expression, and then activated DNA damage repairsignaling pathways, thereby promoting radioresistance and eventual poor outcomes in human cervical cancer." (PMID 33187536, 2020). "We hypothesized that the regulation of HMGB3 on cervical cancer radioresistance was mediated by activation of hTERT transcription." (PMID 33187536, 2020). "Furthermore, we analyzed the correlation between HMGB3/hTERT expression with clinical variables in these cervical cancer patients, and found that high expression of HMGB3/hTERT was related with comparatively higher TNM stage and poorly differentiation." (PMID 33187536, 2020). "Our findings demonstrate that targeting the HMGB3/hTERT axis may be a potential promising for the treatment of cervical cancer." (PMID 33187536, 2020). "The role of HMGB3 and hTERT in cervical cancer should be better to confirm in a larger cohort." (PMID 33187536, 2020). "Our study showed that HMGB3 could bind to hTERT promoter on the region of − 902 to − 321 and induce the expression of hTERT, leading to radioresistance in cervical cancers." (PMID 33187536, 2020). "Our results provide new insights into the mechanism of cervical cancer radioresistance and indicate that targeting the HMGB3/hTERT signaling axis may benefit cervical cancer patients." (PMID 33187536, 2020). "We furtherly study the effect of HMGB3 on radiosensitivity of cervical cancer." (PMID 33187536, 2020). "Thus, miR-142-3p directly targets HMGA1, HMGA2, HMGB1, and HMGB3, inhibiting them through reduction of cell viability, colony formation, migration, and invasion, as well as induction of apoptosis of tumor cells, particularly cervical cancer cells." (PMID 39062899, 2024). "Our findings suggest that HMGB3 may be a new target for cervical cancer radiosensitization." (PMID 33187536, 2020). "HMGB3 as a transcription factor, binds to the promoter region of hTERT andactivates transcriptionally hTERT expression, which leads to radiation resistance of cervical cancer.Targeting HMGB3 /hTERT signaling axis may provide an important strategy in cervical cancer treatment." (PMID 33187536, 2020). "Furthermore, clinical data from 172 cervical cancer patients proved that there was a positive correlation between HMGB3 and hTERT expression, and high expression of HMGB3/hTERT predicted poor response to radiotherapy, worse TNM stages and shorter survival time." (PMID 33187536, 2020). "In this study, we have first identified high-mobility group box 3 (HMGB3) as a new regulator which specifically bind to hTERT promoter and transcriptionally activate hTERT expression in cervical cancer radioresistant cells." (PMID 33187536, 2020). "Nevertheless, there has not yet been a report about the biological function of HMGB3 in regulating cervical cancer radioresistance." (PMID 33187536, 2020). "In the present paper we identified six putative biomarkers (AURKA, DTL, HMGB3, KIF2C, NEK2, and RFC4) which should be further tested to separate indolent HPV related cervical infections from progressive CIN III lesions and for early diagnosis of cervical cancer." (PMID 26701206, 2016).
lung cancer (10 papers, 2019 to 2025). A malignant neoplasm involving the lung. "E2F8 is a transcription factor for the HMGB3 gene whose overexpression is associated with poor prognosis in diverse types of cancer including non‐small cell lung cancer." (PMID 30913346, 2019). "The ΔCt values of HMGB3 in lung cancer patients were 0.55-14.02 (mean: 7.794) and 1.94-14.02 (mean: 7.742) in healthy controls." (PMID 39130876, 2024). "A different analysis found that another autoantibody to HMGB3 was frequently upregulated in the early stages of lung cancer." (PMID 35893814, 2022). "HMGB3 expression was detected in circulating tumor cells in the peripheral blood of patients with lung cancer." (PMID 36397035, 2022). "In the current research, we utilized an RT-PCR-based assay for the identification of HMGB3, survivin, CLCA2, CK7, ASH1, and L587S gene expressions in lung cancer patients." (PMID 39130876, 2024). "In lung cancer samples, the mRNA expression levels of HMGB2 were slightly elevated, and HMGB3 was significantly up-regulated in cancer tissue vs. normal tissues in multiple datasets." (PMID 35923467, 2022).
ovarian carcinoma (10 papers, 2020 to 2025). A malignant neoplasm originating from the surface ovarian epithelium. "The high-mobility group box protein 1 (HMGB1) is a known nucleotide excision repair (NER) cofactor, and its family member HMGB3 has been implicated in chemoresistance in ovarian cancer." (PMID 41009989, 2025). "In the current study, we investigated the function of HMGB3 in ovarian cancer progression and further clarified the underlying mechanisms." (PMID 37328851, 2023). "HMGB3 overexpression led to elevated expression of stemness-associated markers and strengthened ovarian cancer spheroid formation ability, while HMGB3 knockdown had the opposite effect." (PMID 37328851, 2023). "Thus, we determined whether HMGB3 is associated with cisplatin adduct removal in the ovarian cancer cells." (PMID 41009989, 2025). "The slot blot data support this, indicating that cisplatin-specific DNA damage removal is significantly delayed in HMGB3-depleted chemoresistant A2780/CP70 ovarian cancer cells." (PMID 41009989, 2025). "Our previously published studies showed that HMGB3 depletion sensitized cisplatin-resistant A2780/CP70 human ovarian cancer cells to cisplatin and induced apoptosis." (PMID 41009989, 2025). "HMGB3 expression also positively correlates with lymph node metastasis in colorectal, urinary bladder and ovarian cancers." (PMID 39684631, 2024). "HMGB3 promotes the development of malignant phenotypes and stemness of ovarian cancer through the MAPK/ERK signaling pathway." (PMID 39062899, 2024). "Targeted depletion of HMGB3 sensitizes chemoresistant ovarian cancer cells to cisplatin by suppressing the ATR/CHK1/p-CHK1 DNA damage signaling pathway." (PMID 39062899, 2024). "MTT assay showed that HMGB3 knockdown inhibits ovarian cancer cell proliferation, while HMGB3 overexpression significantly promoted the proliferation of these cells." (PMID 37328851, 2023). "Further, HMGB3 promotes PARP inhibitor resistance of ovarian cancer through directly interacting with PARP1." (PMID 37328851, 2023). "HMGB3 promotes ovarian cancer malignant phenotypes and stemness through the MAPK/ERK signaling pathway." (PMID 37328851, 2023). "Blocking MAPK/ERK signaling using AZD6244 or PD0325901 also reversed the increased migration and invasion abilities of ovarian cancer cells induced by HMGB3 overexpression." (PMID 37328851, 2023). "In conclusion, our findings show that HMGB3 promotes ovarian cancer proliferation, mobility, and stemness." (PMID 37328851, 2023). "Further, we clarified that the MAPK/ERK signaling pathway participates in HMGB3-mediated ovarian cancer malignant progression." (PMID 37328851, 2023). "MTT assays demonstrated that HMGB3 overexpression promotes ovarian cancer cell proliferation, while AZD6244 or PD0325901 administration abrogates this effect." (PMID 37328851, 2023). "Consistently, the results of a clonogenic assay also demonstrated that HMGB3 increases the colony formation ability of ovarian cancer cells." (PMID 37328851, 2023). "Our data proved that HMGB3 activates MAPK/ERK signaling in ovarian cancer, as indicated by increased MEK1/2 and ERK1/2 phosphorylation, and the upregulation of its downstream molecules, including ETS-1, CCND1, and c-Myc." (PMID 37328851, 2023). "We further proved that HMGB3 promotes ovarian cancer stemness, proliferation, and metastasis through activating the MAPK/ERK signaling pathway." (PMID 37328851, 2023). "Transwell assays were conducted to investigate metastasis of ovarian cancer cells with HMGB3 overexpressed or knocked down." (PMID 37328851, 2023). "HMGB3 is reported to promote drug resistance through regulating DNA damage response pathways in ovarian cancer." (PMID 37328851, 2023). "HMGB3 knockdown inhibited ovarian cancer cell proliferation and metastasis, whereas HMGB3 overexpression facilitated these processes." (PMID 37328851, 2023).